TXNIP (thioredoxin interacting protein)
Diseases named in the same sentence as TXNIP in open-access papers (continued):
Sharing a sentence is not in itself a finding about the gene and the disease.
liver cancer (15 papers, 2018 to 2025). An epithelial or non-epithelial malignant neoplasm that arises from the liver. "Consistently, hepcidin downregulation was also observed in an experimental liver cancer model of the thioredoxin interacting protein (Tnixp)-deficient mice." (PMID 34277457, 2021). "For example, exosomal miR-27a-3p secreted by M2 macrophages boosts liver CSC traits by reducing the expression of thioredoxin-interacting protein (TXNIP) in liver cancer." (PMID 39578849, 2024). "And moreover, 22 of 32 pairs of liver cancer tissues displayed significantly lower transcriptional level of TXNIP than that in paired margin tissues, and 7 of 10 pairs of BRCA (P = 0.0002 and P = 0.0087, respectively)." (PMID 35843949, 2022). "Initially, we aimed to compare the levels of TXNIP expression in various epithelial- and mesenchymal-like liver cancer cell lines." (PMID 30627326, 2018). "The expression level of TXNIP was lower in primary tumor tissues than that in normal solid tissues, and low TXNIP expression was associated with poor prognostic outcomes in liver cancer patients, suggesting a potential role for TXNIP in suppressing liver cancer growth." (PMID 41249136, 2025). "It has been suggested that TXNIP could be a new promising drug target for liver cancer." (PMID 33194655, 2020). "Next, we measured ROS levels of two HCC cell lines with no basal TXNIP expression (HuH-7, HepG2) and two liver cancer cell lines with high endogenous TXNIP expression (SNU-449 and SK-HEP-1) by fluorescent microscopy and spectrofluorometry." (PMID 30627326, 2018). "TXNIP was absent or significantly reduced in less motile and invasive epithelial-like liver cancer cell lines HuH-7, HepG2 and PLC/PRF/5, while being up-regulated in highly motile and invasive lines SNU-182, -387, -423, -449, -475 and SK-HEP-1 at both mRNA and protein levels." (PMID 30627326, 2018).
Cerebral ischemia (14 papers, 2018 to 2025). Restriction of arterial blood supply to the brain associated with insufficient oxygenation to support the metabolic requirements of the tissue. "It is worth knowing that TXNIP knockdown or its inhibitor(s) holds promise as a therapeutic strategy for cerebral ischemia/reperfusion injury." (PMID 40643515, 2025). "Increased levels of TXNIP and NLRP3 in mice with cerebral ischemia/reperfusion injury is implicated to be pivotal in the development of neuroinflammation." (PMID 40643515, 2025). "LRP1 activation has been shown to attenuate oxidative stress, neuroinflammation and apoptosis and can improve short- and long-term neurological deficits and positively influence mortality after cerebral ischemia by inhibiting the TXNIP/NLRP3 signaling pathway." (PMID 38067191, 2023). "A recent study in cerebral ischemia/reperfusion injury suggested that inhibition of TXNIP/NLRP3 promoted the transition of microglia from M1 to M2 phenotype." (PMID 36875102, 2023). "Our study demonstrated that ER-mediated upregulation of SIRT6 inhibited microglia activation and potentiated angiogenesis in cerebral ischemia via suppressing TXNIP." (PMID 35562171, 2022). "In conclusion, we have demonstrated that ER-mediated upregulation of SIRT6 inhibited microglia activation and potentiated angiogenesis in cerebral ischemia via suppressing TXNIP in vitro." (PMID 35562171, 2022). "Nrf2 is reported to inhibit the NLRP3 inflammasome by regulating the TRX/TXNIP complex and consequently hampers cerebral ischemia reperfusion injury." (PMID 33567593, 2021). "This study suggests that Nrf2 inhibits NLRP3 inflammasome activation during cerebral ischemia/reperfusion injury by regulating the Trx1/TXNIP complex." (PMID 34526897, 2021). "TXNIP is also of growing interest to those who study neurological diseases, including cerebral ischemia, as previously reviewed." (PMID 33567593, 2021). "Studies have shown that Nrf2 can inhibit the formation of NLRP3 inflammasomes through thioredoxin-1 (Trx1)/thioredoxin interacting protein (TXNIP) during cerebral ischemia-reperfusion injury, thereby playing a protective role in the brain." (PMID 34526897, 2021). "Nrf2 prevents NLRP3 inflammasome activation by regulating Trx1/TXNIP complex in cerebral ischemia-reperfusion injury." (PMID 31920652, 2019). "SIRT6 and TXNIP might be involved in the regulation of cerebral ischemia-induced microglial activation and angiogenesis." (PMID 35562171, 2022). "Moreover, TXNIP expression increases in the cytoplasm of neurons with significant brain damage due to focal cerebral ischemia in mice." (PMID 33567593, 2021). "When TXNIP and NLRP3 are decreased, tissue damage associated with cerebral ischemia is reduced." (PMID 33567593, 2021). "TXNIP might be an important downstream molecule of SIRT6 during cerebral ischemia." (PMID 35562171, 2022). "In the context of cerebral ischemia, energy restriction-induced SIRT6 has been found to inhibit TXNIP transcription and promote angiogenesis, which is critical for tissue repair and recovery after cerebral ischemia." (PMID 37627275, 2023). "Cerebral ischemia induces activation of the inflammasome and is characterized by an increase in NLRP3 and TXNIP." (PMID 33567593, 2021). "In this study, we found that IF or ER mimetics protected against cerebral ischemia-induced impairment and microglial activation and potentiated middle cerebral artery occlusion (MCAO)-induced angiogenesis, and accompanied by changes in expression of SIRT6, TXNIP, and NLRP3 inflammasome." (PMID 35562171, 2022).
ischemia (14 papers, 2013 to 2023). A hypoperfusion of the BLOOD through an organ or tissue caused by a PATHOLOGIC CONSTRICTION or obstruction of its BLOOD VESSELS, or an absence of BLOOD CIRCULATION. "Our results suggest that STS inhibits the activity of NLRP3 inflammasome through the suppression of TXNIP expression, which is similar to the conclusion that STS protects against ischemia/reperfusion myocardial injury by inhibiting the TXNIP over-expression." (PMID 37697234, 2023). "Some scholars believe that TXNIP/NLRP3 axis is involved in renal ischemia-reperfusion injury and T2DM cardiomyopathy in diabetic rats." (PMID 35845136, 2022). "Many other original compounds with antioxidant properties are able to decrease the expression of TXNIP and attenuate brain damage and neurotoxicity following ischemia by suppressing the activation of the inflammasome." (PMID 33567593, 2021). "Thanks to a transgenic model, TXNIP deletion is also involved in reducing the deleterious effects of a fatty diet in the revascularization of the lower limbs after ischemia." (PMID 33567593, 2021). "Based on these results, it appears that the expression of TXNIP can be upregulated or downregulated by ischemia, depending on the cell type and the pathological context." (PMID 33567593, 2021). "Here, we examine the impact of modulating thioredoxin interacting protein (TXNIP) to the inflammatory secondary damage and visual impairment in a model of ischemia/reperfusion (IR)." (PMID 31443163, 2019). "Enhanced production of TXNIP is induced by various types of cellular stress, including ischemia." (PMID 37368371, 2023). "Given the crucial role of glucose supply in the cardiac response to ischemia and the role of TXNIP in glucose uptake via GLUT1, it is likely that the resulting increase in glucose supply is due to TXNIP deficiency, and it provides cardioprotection to the ischemic heart." (PMID 33567593, 2021). "We also examined the effect of TXNIP on NLRP3 activation; after ischemia AKI injury, kidney NLRP3 inflammasome expression was dramatically increased in both DI/R rats and NI/R rats as compared to rats of each sham group." (PMID 27867451, 2016). "The present study was designed to investigate the role of TXNIP during ischemia AKI in diabetic models and examine a key role of TXNIP in bridging redox signals with activation of NLRP3 inflammasome in AKI injury." (PMID 27867451, 2016). "Meanwhile, after myocardial infarction, TXNIP reduced HIF-1α and VEGF levels suppressed angiogenesis, enhanced apoptosis and ultimately determined a poor prognosis for the myocardium injury due to ischemia." (PMID 37368371, 2023). "Overexpression of Homer1 could inhibit ER stress-related TXNIP/NLRP3-mediated pyroptosis by regulating the AMPK signaling pathway, which in turn improved the visual function of the retina after ischemia." (PMID 38069134, 2023). "The intramyocardial injection of anti-TXNIP siRNA also decreases the size of the infarction and the activation of NLRP3, which suggests the value of targeting TXNIP to prevent deleterious effects of ischemia." (PMID 33567593, 2021). "Deletion of TXNIP prevented HFD- and ischemia-induced nitrotyrosine levels compared to TKO-ND." (PMID 28661427, 2017).
ischemic stroke (14 papers, 2016 to 2025). A stroke disorder caused by obstruction of blood flow to the brain, due to thrombotic (local blood clot formation) or embolic (due to a blood clot or other material traveling from another site) event. "This study investigates the endothelial cell-specific role of Thioredoxin interacting protein (TXNIP) in ischemic stroke and its underlying molecular mechanisms both in vitro and in vivo." (PMID 39690856, 2025). "Collectively, these studies underscore the critical role of TXNIP in angiogenesis and its potential as a therapeutic target in ischemic stroke." (PMID 39690856, 2025). "As expected, TXNIP knockdown reduced the levels of NLRP3, ASC, pro-caspase-1, and IL-1β proteins, indicating that TXNIP’s role in ischemic stroke is associated with the NLRP3 inflammasome pathway." (PMID 39690856, 2025). "This indicates that TXNIP plays a critical role in promoting NLRP3 inflammasome activation during ischemic stroke." (PMID 39690856, 2025). "To further verify the effect of TXNIP in ischemic stroke in vivo, we established a MACO model in mice." (PMID 39690856, 2025). "A previous study revealed that TXNIP aggravates oxidative stress injury by regulating the MAPK-Nrf2 axis in ischemic stroke." (PMID 39690856, 2025). "In the present study, we found that TXNIP knockdown enhanced cell proliferation, promoted angiogenesis, suppressed cellular inflammation, and attenuated brain damage in ischemic stroke mouse models." (PMID 39690856, 2025). "In this study, we focus on the role of TXNIP in endothelial cells using bEnd.3 cells and animal models of ischemic stroke." (PMID 39690856, 2025). "In conclusion, TXNIP knockdown can suppress inflammation, promote cell proliferation, and enhance angiogenesis in vitro, thereby mitigating cerebral damage in ischemic stroke mouse models." (PMID 39690856, 2025). "A prior study revealed that TXNIP overexpression induced blood–brain barrier disruption in ischemic stroke and myocardial ischemia/reperfusion injuries." (PMID 36830671, 2023). "In conclusion, our results indicated that TENS alleviated brain damage following ischemic stroke via inhibiting neuronal oxidative stress and pyroptosis and activating mitophagy, possibly via the regulation of TXNIP, BRCC3/NLRP3, and HIF-1α/BNIP3 pathways." (PMID 37101593, 2023). "We reported for the first time that HG with tPA-reperfusion increased the expression level of TXNIP protein, which in turn increased, oxidative damage, inflammation and neuronal cell death and dysfunction in ischemic stroke." (PMID 34681207, 2021). "It has also been documented that myrrh exerts a neuroprotective effect by regulating the TXNIP/NLRP3 axis in ischemic stroke to reduce ROS-mediated ferroptosis." (PMID 34059091, 2021). "After ischemic stroke, TXNIP exacerbates cerebral injury through redox imbalance and subsequently activates the NLRP3 inflammasome." (PMID 34059091, 2021). "TXNIP is overexpressed in ischemic-stroke–induced blood–brain barrier dysfunction and myocardial ischemia/reperfusion injuries." (PMID 33803178, 2021). "This suggests that TXNIP-mediated activation of the NLRP3 inflammasome is a key factor in ischemic stroke." (PMID 34059091, 2021). "Linking oxidative stress to inflammation in ischemic stroke, the inhibition of thioredoxin-interacting protein (TXNIP) was shown to decrease the activation of inflammasome-dependent pathways." (PMID 31998437, 2020). "Wild-type, TXNIP knockout, and wild-type mice treated with the TXNIP inhibitor resveratrol were subjected to middle cerebral artery occlusion (MCAO) to model ischemic stroke." (PMID 33302545, 2020). "Similarly, global knocking down of TXNIP provides neuroprotection through inactivation of inflammasome-dependent and apoptotic inducing pathways in ischemic stroke." (PMID 34681207, 2021). "So far, the idea to inhibit TXNIP has been elaborated in terms of brain hemorrhage or ischemic stroke, where this protein could serve as a therapeutic target." (PMID 33803178, 2021).
ischemic stroke (continued). "This shows that the TXNIP/NLRP3 inflammasome is an important contributor to ischemic stroke." (PMID 31174550, 2019). "However, the specific implications of targeting TXNIP in ischemic stroke remain poorly understood." (PMID 39690856, 2025). "Moreover, our most recent studies showed that acute HG involves TXNIP upregulation and exacerbates the inflammation and neurovascular damage associated with tPA-reperfusion in filament middle cerebral artery occlusion (MCAO) mouse model of ischemic stroke." (PMID 34681207, 2021). "Thus, inhibiting the expression of TXNIP could decrease the activation of inflammasome following ischemic stroke." (PMID 27589720, 2016). "Ker Gawl., has been shown to have protective effects after ischemic stroke by inhibiting NLRP3, IL-1β, caspase-1 and TXNIP in vitro and in vivo." (PMID 32650482, 2020). "In an ischemic stroke, oxidative stress is the main initiator and it has been shown that NLRP3 activation is achieved by means of a thioredoxin-interacting protein (TXNIP) (endogenous inhibitor of TRX), which is activated by oxidative stress." (PMID 32650482, 2020). "However, the precise alteration in BRCC3 levels and whether TENS exerts counteracting effects on oxidative stress and inflammasomes by TXNIP and BRCC3/NLRP3 signaling have barely been investigated in ischemic stroke." (PMID 37101593, 2023). "Besides, ruscogenin is a crucial steroid sapogenin derived from Ophiopogn japonicus, and ruscogenin could improve neurological dysfunctions of ischemic stroke mice via suppressing expression levels of NLRP3, IL-1β, caspase-1, TXNIP, MAPK, and ROS." (PMID 32581721, 2020). "Thus, inhibiting ROS generation and modulating the TXNIP/NLRP3 pathway might be beneficial for prevention and treatment of ischemic stroke." (PMID 27589720, 2016). "Although NOX2 did not regulate NLRP3 or TXNIP in the umbilical vein endothelial cells, NOX2 deletion attenuated NLRP3 induction in the cerebral cortex of mice after ischemic stroke, as we observed after TBI." (PMID 28785377, 2017). "However, there is still no clear evidence confirming the correlation between TXNIP and the NLRP3 inflammasome in ischemic stroke." (PMID 39690856, 2025).
myocardial ischemia (14 papers, 2013 to 2024). A disorder of cardiac function caused by insufficient blood flow to the muscle tissue of the heart. "Exosomes from M2 macrophages, carrying miR-148a, alleviate myocardial ischemia/reperfusion injury through downregulation of thioredoxin-interacting protein (TXNIP) and inhibition of the TLR4/NF-κB/NLRP3 inflammasome signaling pathway." (PMID 38644472, 2024). "A previous study indicated that TXNIP protein exacerbated cardiomyocyte apoptosis and cardiac dysfunction during myocardial ischemia–reperfusion injury by regulating the formation and clearance of autophagosomes." (PMID 39604027, 2024). "A plethora of inhibitors proposed to hamper post-myocardial ischemia damage inhibit hypoxia-induced TXNIP and NLRP3 expressions." (PMID 33567593, 2021). "M2-Exos carrying miR-148a alleviates myocardial ischemia/reperfusion (MI/R) injury by down-regulating thioredoxin-interacting protein (TXNIP) and through inactivation of the TLR4/NF-κB/NLRP3 inflammasome signaling pathway." (PMID 34368234, 2021). "Wang BF, Yoshioka J. The emerging role of thioredoxin-interacting protein in myocardial ischemia/reperfusion injury." (PMID 34008824, 2021). "In a rat model of myocardial ischemia/reperfusion injury, it was found that exosomes derived from M2 macrophages deliver microRNA-148a and alleviate myocardial ischemia/reperfusion injury by inhibiting thioredoxin interacting protein (TXNIP) and the TLR4/NF-jB/NLRP3 inflammasome signalling pathway." (PMID 38622659, 2024). "However, high expression of TXNIP has also been classified as a biomarker for oxidative stress and myocardial ischemia in heart tissue." (PMID 36860653, 2023). "However, in myocardial ischemia/reperfusion injury, myocardial-specific TXNIP is overexpressed and directly interacts with the autophagy regulatory factor Redd to inhibit mTOR, thereby aggravating cardiac ischemia/reperfusion injury." (PMID 36059548, 2022). "A recent study shows that the interaction between TXNIP and NLRP3 is the key point in the damage-induced myocardial ischemia." (PMID 33567593, 2021). "In recent years, a growing body of research has begun to target TXNIP and thus suppress the ROS-TXNIP-NLRP3 pathway to hamper heart damage in myocardial ischemia." (PMID 33567593, 2021). "In a study on cardiac ischemia-reperfusion, the authors showed that the NLRP3 inflammasome is increased in cardiac endothelial cells via TXNIP." (PMID 33567593, 2021).
bladder cancer (13 papers, 2013 to 2025). "In addition, the authors showed that loss of TXNIP expression facilitates bladder carcinogenesis using a mouse bladder cancer model." (PMID 24376827, 2013). "Together these findings powerfully draw a systematic prognostic landscape for TXNIP and demonstrate that TXNIP is a prognostic biomarker for breast, lung, liver, and bladder cancer." (PMID 35843949, 2022). "TXNIP can also negatively regulate the occurrence of bladder cancer by inhibiting the activation of ERK, which is induced by stromal cell-derived factor-1/C-X-C chemokine receptor type 4 signaling." (PMID 33194655, 2020). "TXNIP is expressed at a lower level in various cancers (such as liver, breast and bladder cancer) and is a multifunctional protein that controls various cellular processes, such as cell proliferation, apoptotic signaling, oxidative stress and inflammation." (PMID 32023548, 2020). "TXNIP can also prevent the occurrence of bladder cancer by inhibiting the activation of ERK, which inhibits apoptosis in bladder cancer cells." (PMID 33194655, 2020). "Recent research has shown that the expression of TXNIP was reduced in human bladder cancer." (PMID 40558539, 2025). "TXNIP is downregulated in bladder cancer based on the grade and stage." (PMID 32511893, 2020). "Likewise, in bladder cancer TXNIP mRNA was significantly decreased in 39 human bladder cancers as compared to 6 normal samples and could be inversely correlated to the grade and stage of bladder cancer." (PMID 33081035, 2020). "Furthermore, one study found that the absence of TXNIP expression promotes the development of bladder cancer in a mouse model." (PMID 40558539, 2025).